MAPT (microtubule associated protein tau)
Diseases named in the same sentence as MAPT in open-access papers (continued):
Sharing a sentence is not in itself a finding about the gene and the disease.
Alzheimer disease (continued). "The microtubule-associated protein tau (MAPT) plays an important role in Alzheimer’s disease and primary tauopathy diseases." (PMID 35082657, 2021). "MAPT is a gene encoding τ protein, which is implicated in the pathogenesis of several neurodegenerative disorders such as Alzheimer’s disease, Parkinson’s disease, and progressive supranuclear palsy." (PMID 34406386, 2021). "The protein product of MAPT, microtubule-associated protein tau, forms hyperphosphorylated neurofibrillary tangles (NFTs), one of the main characteristics of Alzheimer’s disease (AD)." (PMID 33972291, 2021). "Alzheimer’s disease (AD) is characterized by extracellular plaque deposits of amyloid-β (Aβ) peptides and intracellular neurofibrillary tangles (NFTs) of the microtubule associated protein tau." (PMID 33816551, 2021). "A direct link between neurodegeneration and heterochromatin was found in Drosophila: The microtubule-associated protein tau is involved in a number of neurodegenerative disorders, including Alzheimer’s disease." (PMID 33886541, 2021). "Of particular importance was decreased phosphorylation of MAPT, a hallmark protein that is hyperphosphorylated in Alzheimer’s disease." (PMID 34235635, 2021). "Alzheimer’s disease (AD) is neuropathologically characterized by large extracellular plaques of amyloid-beta peptide (Aβ) and intracellular tangles of microtubule-associated protein tau." (PMID 34272583, 2021). "Aggregation of the microtubule-associated protein tau into paired helical filaments (PHFs) and neurofibrillary tangles is a defining characteristic of Alzheimer’s Disease." (PMID 34220446, 2021). "Alzheimer disease is associated with the aggregation and accumulation of two major protein aggregates—intracellular neurofibrillary tangles made up of microtubule-associated protein Tau and extracellular Amyloid-β plaques." (PMID 33962636, 2021). "Alzheimer’s disease (AD) is characterized by intracellular and extracellular protein aggregates in the brain including microtubule-associated protein tau and cleavage products of the amyloid precursor protein, amyloid-beta (Aβ)." (PMID 33806203, 2021). "Abnormal post-translational modifications have been associated with the cytosolic accumulation and a gain of toxic function of the microtubule-associated protein tau in Alzheimer's Disease (AD) and other tauopathies." (PMID 34262517, 2021). "Intracellular aggregates of the microtubule-associated protein tau define Alzheimer’s disease (AD) and related neurodegenerative tauopathies." (PMID 34039426, 2021). "Alzheimer’s disease (AD) is the most prevalent form of dementia, involving beta-amyloid (Aβ) and microtubule-associated protein tau." (PMID 34205516, 2021). "Microtubule-associated protein tau assists in stabilizing microtubules and has been particularly implicated in Alzheimer's disease (AD)." (PMID 32226410, 2020). "The MAPT H2 haplotype is associated with lower Alzheimer's disease (AD) risk in large cohorts and lower brain MAPT levels." (PMID 32400971, 2020). "In vivo, [18F]flortaucipir retention has been shown to correlate well with post mortem tau pathology in MAPT R406W mutation gene carriers and to Alzheimer’s disease-related tau pathology." (PMID 31612245, 2020). "MAPT transcripts are differentially expressed within the nervous system and mutations in MAPT have been linked to neurodegenerative disorders, such as Alzheimer’s disease, frontotemporal dementia, and cortico-basal degeneration." (PMID 30867560, 2020). "Genetic susceptibility clearly appears to play an etiologic role for EOD, including APP and PSEN1/2 gene mutations for Alzheimer’s dementia (AD) and MAPT, GNR and C9ORF72 for frontotemporal dementia (FTD)." (PMID 33138082, 2020). "Mutations in the MAPT gene are associated with a variety of neurodegenerative diseases, such as Alzheimer's disease, frontotemporal dementia, and cortical basal cell degeneration." (PMID 32090979, 2020).
Alzheimer disease (continued). "Previous studies in our lab have utilized lysate-purified rAAV2/8 to express the human microtubule associated protein tau (MAPT) in BSC in order to model pathological changes found in Alzheimer’s Disease." (PMID 32122372, 2020). "Pathological accumulation of microtubule associated protein tau in neurons is a major neuropathological hallmark of Alzheimer’s disease (AD) and related tauopathies." (PMID 32208437, 2020). "Comparable to our observations, human microtubule-associated protein Tau in an Alzheimer's disease mouse model accumulated in rod bipolar cells in the inner retina." (PMID 32503050, 2020). "Neurodegenerative disorder Alzheimer’s disease (AD) is identified by the continuous loss of neurons, deposition of insoluble aggregates of two proteins in the brain, amyloid-β (Aβ) and the microtubule-associated protein tau (MAPT)." (PMID 33260759, 2020). "The microtubule-associated protein Tau (MAPT) accumulates in the brain of numerous neurological conditions, including Alzheimer’s disease (AD), Fronto-temporal Dementia, Progressive Supranuclear Palsy, and Chronic Traumatic Encephalopathy (CTE)." (PMID 32611392, 2020). "The microtubule-associated protein tau is closely correlated with hypometabolism in Alzheimer’s disease (AD)." (PMID 32973490, 2020). "In Alzheimer’s disease (AD), both amyloid-beta (Aβ) and hyperphosphorylated microtubule-associated protein tau (MAPT/TAU), the two main pathological hallmarks of AD, accumulate in mitochondria resulting in functional impairment and ROS generation." (PMID 32987701, 2020). "These diseases include frontotemporal dementia (FTD) and Alzheimer’s disease (AD) and can be sporadic or inherited when caused by mutations in the MAPT gene." (PMID 33255694, 2020). "MAPT H1 haplotype is implicated as a risk factor for neurodegenerative diseases including Alzheimer's disease (AD)." (PMID 32400971, 2020). "Perhaps the best-known pathological associations of MAPT are Parkinson’s and Alzheimer’s diseases, with evidence for genetic overlap between these two neurodegenerative disorders within this extended MAPT region." (PMID 31504236, 2019). "Many of these diseases, including Alzheimer's disease (AD), induce neurodegenerative and pathological processes via the abnormal accumulation of the microtubule‐associated protein tau (MAPT)." (PMID 30809950, 2019). "MAPT gene mutations have been associated with several neurodegenerative disorders such as Alzheimer’s disease and Parkinson’s disease." (PMID 31001319, 2019). "The accumulation of the microtubule-associated protein tau (MAPT) within central neurons is a key histopathological feature of Alzheimer’s disease (AD)." (PMID 31551716, 2019). "The pathological hallmarks of Alzheimer’s disease (AD) are the presence of extracellular senile plaques containing amyloid β (Aβ) peptide, and intracellular neurofibrillary tangles of the microtubule-associated protein tau." (PMID 30344488, 2018). "The microtubule-associated protein tau (MAPT) is involved in the pathogenesis of several forms of dementia, including Alzheimer’s disease (AD) and frontotemporal dementia (FTD)." (PMID 29590627, 2018). "Misfolding of microtubule-associated protein tau (MAPT) within neurons into neurofibrillary tangles is an important pathological feature of Alzheimer’s disease (AD)." (PMID 30227881, 2018). "We selected six Alzheimer’s disease patients (two Braak I, two Braak IV, two Braak VI) and 4 patients with Fronto-temporal dementia associated with a mutation of MAPT gene (two P301L, one P332S and one G389R)." (PMID 30497516, 2018). "The development of insoluble, intracellular neurofibrillary tangles composed of the microtubule-associated protein tau is a defining feature of tauopathies, including Alzheimer’s disease (AD)." (PMID 30068389, 2018).
Alzheimer disease (continued). "For example, in Alzheimer’s disease misfolding and aggregation of amyloid-β and microtubule-associated protein tau (MAPT), occur in a cascade that ultimately impacts on synaptic function and cell survival." (PMID 30060017, 2018). "Carbazole and 2-arylquinoline binding was only observed in cases with Alzheimer’s disease and one case with frontotemporal dementia and parkinsonism linked to chromosome 17 exhibiting a R406W MAPT mutation." (PMID 29716656, 2018). "Mutations on MAPT have been associated with several neurodegenerative disorders such as Alzheimer’s disease (AD), Pick’s disease, frontotemporal dementia, cortico-basal degeneration, and progressive supranuclear palsy." (PMID 29378629, 2018). "Tauopathies are a class of neurodegenerative diseases associated with the microtubule-associated protein tau, with Alzheimer’s disease (AD) being the most prevalent related disorder." (PMID 29584657, 2018). "For example, Alzheimer’s disease shows both amyloid-β and microtubule-associated protein tau (MAPT) in the form of neuritic plaques and neurofibrillary tangles, with clinical progression correlating exclusively with neurofibrillary tangle burden." (PMID 28334843, 2017). "Microtubule associated protein tau (MAPT) is involved in the pathogenesis of Alzheimer's disease and many forms of frontotemporal dementia (FTD)." (PMID 28484365, 2017). "Polymorphisms in the MAPT gene are also involved in the pathologies of Alzheimer's disease (AD), progressive supranuclear palsy (PSP), and corticobasal degeneration (CBD)." (PMID 28239348, 2017). "Several SNPs associated with risk for Alzheimer’s disease (AD) were identified near MAPT and KANSL1 in humans and they appeared to be correlated with an overexpression of both genes in different brain regions." (PMID 28704368, 2017). "To validate the method, we have confirmed the binding of HuD to the 3′-UTR of the mRNA for the microtubule-associated protein tau, implicated in the pathogenesis of Alzheimer’s disease." (PMID 32161791, 2017). "Microtubule-associated protein tau is the major component of paired helical filaments (PHFs) associated with the neuropathology of Alzheimer’s disease (AD)." (PMID 27548710, 2016). "Alzheimer’s disease (AD) researchers have struggled for decades to draw a causal link between extracellular Aβ aggregation and intraneuronal accumulation of microtubule-associated protein tau." (PMID 27070146, 2016). "The microtubule-associated protein tau has a critical role in Alzheimer disease and related tauopathies." (PMID 27030011, 2016). "The H2 haplotype is related in some studies to late onset Alzheimer’s disease and frontotemporal dementia risk; it is also associated with lower brain MAPT expression levels in Alzheimer’s disease (AD) patients." (PMID 27458716, 2016). "Mutations in APP, APOE, PSEN1, PSEN2 and MAPT genes were found to cause Alzheimer’s disease pathogenesis." (PMID 26784894, 2016). "MAPT is a gene that is alternatively spliced to create the tau proteins, which are implicated in Alzheimer's disease, neural crest development and neuronal differentiation." (PMID 26337082, 2015). "Microtubule associated protein tau is the major component of the neurofibrillary tangles (NFTs) found in the brains of patients with Alzheimer’s disease and several other neurodegenerative diseases." (PMID 25881209, 2015). "Aggregation of microtubule associated protein tau is one of cause of neuronal loss in tauopathies including Alzheimer's disease." (PMID 26671725, 2015). "For example, hyper-phosphorylation of Tau proteins is implicated in Alzheimer’s disease, and ActiveDriver predicts the corresponding MAPT gene as significantly enriched in PTM-related substitutions (FDR p = 0.0011)." (PMID 25611800, 2015). "In Alzheimer’s disease (AD), dissociation and mis-sorting of the axonal microtubule-associated protein tau and cytoskeletal disruptions are linked to transport deficits and synaptic dysfunction." (PMID 26321907, 2015).
Alzheimer disease (continued). "Protein aggregates can be seen in other neurodegenerative disorders, for example Aβ and microtubule-associated protein tau in Alzheimer’s disease or αSYN in Parkinson’s disease." (PMID 26694349, 2015). "There are also multiple kinases phosphorylating the microtubule associated protein tau (MAPT), a protein known to be involved in Alzheimer's disease and associated to PD in GWAS." (PMID 25120428, 2014). "The brain-enriched microtubule-associated protein tau, a critical regulator of cytoskeletal dynamics, forms insoluble aggregates in a number of neurodegenerative diseases termed tauopathies, including Alzheimer's disease (AD)." (PMID 24618580, 2014). "The microtubule-associated protein tau is a principal component of neurofibrillary tangles, and has been identified as a key molecule in Alzheimer's disease and other tauopathies." (PMID 24298146, 2014). "Hyperphosphorylation of microtubule-associated protein tau is one of the major pathological events in Alzheimer’s disease (AD) and other related neurodegenerative diseases, including frontotemporal dementia with parkinsonism linked to chromosome 17 (FTDP-17)." (PMID 25076872, 2014). "The kinase Fyn, the microtubule-associated protein tau and the peptide amyloid-β (Aβ) constitute a toxic triad in Alzheimer's disease (AD)." (PMID 24860422, 2014). "MAPT encodes for tau, the predominant component of neurofibrillary tangles that are neuropathological hallmarks of Alzheimer’s disease (AD)." (PMID 25324900, 2014). "The intracellular aggregates of microtubule-associated protein Tau called neurofibrillary tangles are one of the important hallmarks of Alzheimer disease." (PMID 24284393, 2013). "The Alzheimer Disease (AD) brain accumulates intracellular neurofibrillary tangles, composed primarily of the microtubule associated protein tau and extracellular amyloid-β plaques." (PMID 24278327, 2013). "Pathologic aggregation of β-amyloid (Aβ) peptide and the axonal microtubule-associated protein tau protein are hallmarks of Alzheimer's disease (AD)." (PMID 23372648, 2013). "Phosphorylated forms of microtubule-associated protein tau accumulate in neurofibrillary tangles in Alzheimer's disease." (PMID 23601672, 2013). "GSK-3β is widely implicated in several cellular pathways and, in the context of Alzheimer’s disease, associated with the hyperphosphorylation of the microtubule-associated protein tau." (PMID 23875003, 2013). "In the case of Alzheimer's disease (AD) these are extracellular plaques of Aβ and intracellular filaments of the microtubule-associated protein tau, whilst α-synuclein deposits typify Lewy pathology disorders, including Parkinson's disease (PD)." (PMID 23797088, 2013). "Genetic variants in PPP3R1 and MAPT have been shown to be associated with cerebrospinal fluid p-tau levels and rate of decline in Alzheimer's disease patients in three independent samples." (PMID 23984328, 2013). "Polymorphisms in the gene encoding GSK-3β (GSK3B) have been associated with Alzheimer’s disease and frontotemporal dementia, and an epistatic interaction between GSK3B and MAPT has been associated with Parkinson’s disease and Alzheimer’s disease." (PMID 23951236, 2013). "In Alzheimer disease (AD) and other tauopathies, microtubule-associated protein tau becomes hyperphosphorylated, undergoes conformational changes, aggregates, eventually becoming neurofibrillary tangles (NFTs)." (PMID 23882258, 2013). "Hyperphosphorylated tau forms neurofibrillary tangles in Alzheimer's disease brains, and mutations of MAPT cause frontotemporal dementia with parkinsonism linked to chromosome 17 (FTDP-17)." (PMID 22623900, 2012). "A well-known representative of this class of proteins is the microtubule-associated protein tau, which is of particular interest for its role in several neurodegenerative diseases, including Alzheimer's disease and Frontemporal Dementia." (PMID 22529924, 2012).
Alzheimer disease (continued). "Abnormal hyperphosphorylation of microtubule-associated protein tau plays a crucial role in neurodegeneration in Alzheimer's disease (AD)." (PMID 22536363, 2012). "In Alzheimer's disease (AD) and other tauopathies, the microtubule-associated protein tau can undergo aberrant hyperphosphorylation potentially leading to the development of neurofibrillary pathology." (PMID 21304998, 2011). "Members of the CK1 family reportedly play an important role in cytoskeletal rearrangements by mediating hyperphosphorylation of the microtubule-associated protein tau, which is associated with Alzheimer's disease." (PMID 21698236, 2011). "In Alzheimer's disease (AD) brains, the microtubule-associated protein tau and amyloid-β (Aβ) deposit as intracellular neurofibrillary tangles (NFTs) and extracellular plaques, respectively." (PMID 22174735, 2011). "Tauopathies, including Alzheimer's disease, are characterized by abnormal intraneuronal accumulation of the microtubule-associated protein tau." (PMID 20664788, 2010). "For instance, the microtubule-associated protein tau is abnormally phosphorylated in Alzheimer's disease as is α-synuclein in Parkinson's disease." (PMID 20804554, 2010). "Microtubule-associated protein-tau (MAPT), which is implicated in the pathogenesis of Alzheimer's disease, is associated with another mechanism of taxane resistance." (PMID 20579400, 2010). "The microtubule associated protein tau is the principle component of neurofibrillar tangles, which are a characteristic marker in the pathology of Alzheimer's disease; similar lesions are also observed after chronic alcohol abuse." (PMID 17241479, 2007). "Similarly, ‘microtubule associated protein tau’ (MAPT), one of the main pathological proteins of Alzheimer's disease, showed one of the highest positive fold changes but also a large variability." (PMID 40491829, 2025). "While MAPT mutations are more common in Frontotemporal Dementia, several missense App mutations have been associated with elevated risk for familial or Early-Onset Alzheimer’s Disease (EOAD)." (PMID 41509440, 2025). "Alzheimer’s disease (AD) is characterized by the pathological accumulation of Aβ and the formation of intraneuronal neurofibrillary tangles, which result from the aggregation of hyperphosphorylated microtubule associated protein tau (MAPT)." (PMID 40026845, 2025). "The leading locus encompasses MAPT, encoding the tau protein central to Alzheimer's disease." (PMID 41044200, 2025). "Furthermore, the expression level of the microtubule-associated protein tau (MAPT) gene, which is frequently mutated in Alzheimer's disease, is regulated by Praja2." (PMID 41182881, 2025). "Tauopathies comprise a group of neurodegenerative disorders, including Pick’s disease, frontotemporal dementia (FTD), and Alzheimer’s diseases (AD), that are defined by abnormal aggregation of the microtubule-associated protein tau (MAPT) and progressive dementia." (PMID 41509366, 2025). "The microtubule-associated protein tau has gained significant attention over the last several decades primarily due to its apparent role in the pathogenesis of several diseases, most notably Alzheimer’s disease." (PMID 38102924, 2024). "Interestingly, a region on chromosome 17 corresponding to the microtubule-associated protein tau, a known risk locus for Alzheimer’s disease, was shared among patients with glaucoma, optic nerve degeneration traits, and Alzheimer’s." (PMID 37834380, 2023). "Also, the hyperphosphorylation of the microtubule associated protein Tau facilitates its aggregation and formation of neurofibrillary tangles (NFTs), which are involved in synaptic disruption and neurodegeneration in Alzheimer’s disease." (PMID 37575967, 2023). "Both Parkinson’s and Alzheimer’s disease have been linked to MAPT." (PMID 38239489, 2023).